ZNF80 (zinc finger protein 80)
Description:
May be involved in transcriptional regulation.
Synonyms: pT17
Tractability: No criterion of Open Targets' tractability assessment is met for any kind of drug.
Gene: Protein-coding gene on chromosome 3 (114,234,631 to 114,237,578, reverse strand). Ensembl gene ENSG00000174255.
Subcellular location: Nucleus
Subcellular location (Human Protein Atlas): Nucleoli; Nucleoplasm
Gene Ontology:
Molecular function: protein binding; DNA-binding transcription factor activity, RNA polymerase II-specific; RNA polymerase II transcription regulatory region sequence-specific DNA binding
Biological process: regulation of transcription by RNA polymerase II
Cellular component: nucleus
Genetic constraint (gnomAD): Loss-of-function variants: 0 observed, 0.2 expected, observed/expected ratio (o/e) 0, 90% interval 0 to 1.88. That is too few expected variants to judge how well the gene tolerates losing a copy. Missense variants: 394 observed, 352.09 expected, observed/expected ratio (o/e) 1.12, 90% interval 1.03 to 1.22. Synonymous variants: 132 observed, 128 expected, observed/expected ratio (o/e) 1.03, 90% interval 0.89 to 1.19.
Homologues: Orthologues: chimpanzee ZNF80 (96% identical), Drosophila melanogaster CG3281 (31% identical), Drosophila melanogaster CG2712 (29% identical), Drosophila melanogaster Phs (24% identical). Paralogues in human: ZNF599 (52% identical), ZNF805 (47% identical), ZNF264 (47% identical), ZNF404 (46% identical), ZNF582 (46% identical), ZFP37 (45% identical), ZNF25 (44% identical), ZNF619 (42% identical), ZNF70 (42% identical), ZNF266 (42% identical), ZNF35 (42% identical), ZNF439 (42% identical), and 50 more.
Diseases named in the same sentence as ZNF80 in open-access papers:
ZNF80 is named in the same sentence as 6 diseases in open-access papers, as found by Europe PMC text mining. Sharing a sentence is not in itself a finding about the gene and the disease.
ZNF80 shares sentences with these, for which no sentence is quoted: aging (1 paper); enteropathy (1); genetic disorder (1); Intellectual disability (1); Primrose syndrome (1); tumor (1).